SALL2 (spalt like transcription factor 2)
Diseases named in the same sentence as SALL2 in open-access papers (continued):
Sharing a sentence is not in itself a finding about the gene and the disease.
leukemia (5 papers, 2015 to 2022). A malignant (clonal) hematologic disorder, involving hematopoietic stem cells and characterized by the presence of primitive or atypical myeloid or lymphoid cells in the bone marrow and the blood. "SALL2 has also been associated with induction of cellular quiescence in human fibroblasts and with cellular apoptosis in mouse embryonic fibroblast and human leukemia cells exposed to genotoxic stress." (PMID 29689621, 2018). "We also previously demonstrated that SALL2 induces apoptosis of MEFs and human leukemia cells exposed to genotoxic stress." (PMID 29689621, 2018). "SALL2 is downregulated in many malignancies, including gastrointestinal tumours, ovarian tumours, and certain types of leukaemia." (PMID 29228922, 2017). "The Sall2-dependent doxorubicin-induced Noxa expression was also confirmed in Jurkat T leukemia cells, suggesting that the Sall2/Noxa axis happens in a cancer cell context." (PMID 26181197, 2015). "To demonstrate the relevance of the Sall2/Noxa axis in a human cancer cell model, we used Jurkat leukemia T cell." (PMID 26181197, 2015). "Recently, SALL2 was found downregulated in various types of cancer, including leukemia, ovarian, lung, and radioresistant esophageal cancers, suggesting that SALL2 may act as a tumor suppressor." (PMID 31657150, 2019). "In addition, studies in leukemia Jurkat T cells support the existence of the Sall2/Noxa axis, and the significance of this axis on the apoptotic response to doxorubicin in cancer cells." (PMID 26181197, 2015). "Since we saw relevant differences in the SALL2 and JUP expressions in leukemia patients in contrast to healthy bone marrow samples, we determined whether the expressions of these genes were related to better overall survival." (PMID 36428851, 2022).
synovial sarcoma (5 papers, 2006 to 2018). "Many tumours, such as synovial sarcomas and tongue squamous cell carcinomas, exhibit high levels of SALL2 expression." (PMID 29228922, 2017). "Sall2 overexpression has been reported in some tumors such as Wilm’s tumor, synovial sarcomas, squamous cell carcinoma (SCC) of the tongue, and Testicular Germ Cell tumor (TGC)." (PMID 24040083, 2013). "However, SALL2 is found upregulated in Wilms tumor, synovial sarcoma, and oral and testicular cancer, indicating that SALL2 role in cancer is yet controversial." (PMID 29689621, 2018). "Furthermore, cDNA expression profiling on soft tissue tumors identified SALL2 in a group of genes characteristically expressed by synovial sarcomas." (PMID 24040083, 2013). "Additionally, many other genes that have been previously related to synovial sarcomas, such as the SSX4 gene, EGFR and SALL2, components of the retinoic acid pathway (CRABP1 and RARG) as well as retinoic acid induced genes (IRX5 and TGFβ2), were also included in this module." (PMID 16503973, 2006).
colon cancer (4 papers, 2013 to 2025). "Moreover, employing the SurvExpress platform, we found evidence that colon cancer patients with higher cancer risk exhibited lower levels of SALL2 and AXIN2 compared to those with lower cancer risk." (PMID 40869218, 2025). "Our research showed that SALL2 is associated with an enhanced cell death response to XAV939 in colon cancer cells compared to CRC cells lacking SALL2." (PMID 40869218, 2025). "Similarly, Silmitasertib transiently increased SALL2 protein levels in SW480 colon cancer cells and H1299 human lung cancer cells." (PMID 38493149, 2024). "According to the overall SALL2 expression, the E1A isoform is highly predominant in brain cancer and absent in colon cancer, supporting its association with these cancers." (PMID 33692826, 2021). "Studies have shown that SALL2 mRNA levels are diminished in several types of cancer, with a particularly significant reduction in the SALL2E1A isoform mRNA in colon cancer." (PMID 40869218, 2025).
esophageal cancer (4 papers, 2019 to 2022). A primary or metastatic malignant neoplasm involving the esophagus. "Although this study did not associate SALL2-dependent PTEN regulation with cell migration, previous studies demonstrated that SALL2 expression correlated with impaired cell migration in human ovarian and esophageal carcinoma cell lines." (PMID 34944911, 2021).
lung carcinoma (4 papers, 2013 to 2024). "Consistently, SALL2-4A exhibited a trend towards increased stability compared to SALL2 4D or single Alanine mutants in the H1299 lung cancer cell line." (PMID 38493149, 2024).
melanoma (4 papers, 2015 to 2024). A malignant, usually aggressive tumor composed of atypical, neoplastic melanocytes. "We confirmed the overlapped immunofluorescent signals of CDKAL1 and SALL2 in RMS cells, as well as melanoma, liver cancer, prostate cancer, and stomach cancer." (PMID 36786012, 2023).
colorectal cancer (3 papers, 2021 to 2025). A primary or metastatic malignant neoplasm that affects the colon or rectum. "Collectively, these findings identify SALL2 as a negative regulator of Wnt/β-catenin signaling and support its potential as a prognostic biomarker and therapeutic target in colorectal cancer." (PMID 40869218, 2025). "Our findings support a tumor suppressor role for SALL2 in colorectal cancer, mediated in part through a previously unrecognized SALL2-dependent regulatory mechanism involving AXIN2, a key negative modulator of Wnt/β-catenin signaling." (PMID 40869218, 2025). "Here, we have demonstrated that SALL2 increases the Silmitasertib cytotoxicity in SW480 colorectal cancer cells and in AKP-derived organoids, a valid alternative to animal treatment that supports the relevance of the association between CK2 and SALL2." (PMID 38493149, 2024). "SALL2 expression is upregulated in brain and testis tumors (p-value 1.66e-99 and 1.29e-40, respectively) but significantly downregulated in colorectal cancer tumors (p-value 1.72e-90) (asterisk)." (PMID 33692826, 2021). "However, no functional studies have been conducted on SALL2 in colorectal cancer." (PMID 40869218, 2025).
Wilms tumor (3 papers, 2013 to 2018). An embryonal neoplasm characterized by the presence of epithelial, mesenchymal, and blastema components. "Microarray studies identified SALL2 as one of the 27 signature-genes highly expressed in Wilm’s tumor." (PMID 24040083, 2013). "Still, understanding how upregulation of SALL2 in Wilm’s tumors and other cancers affects tumor biology awaits further studies." (PMID 24040083, 2013). "In addition, WT1 was shown to repress SALL2 promoter activity, which may provide an explanation for the upregulation of SALL2 in Wilm’s tumors resulting from WT1 inactivation." (PMID 24040083, 2013).
Alport syndrome (2 papers, 2013 to 2015). A rare renal disease characterized by glomerular nephropathy with hematuria progressing to end-stage renal disease (ESRD), frequently associated with sensorineural deafness, and occasionally with ocular anomalies. "Sequencing of these candidate genes most likely associated with kidney defects and proteinuria revealed 2 mutations in COL4A3 gene, a gene associated with Alport syndrome and SALL2, a gene associated with urinary tract development." (PMID 24130771, 2013).
esophageal squamous cell carcinoma (2 papers, 2021 to 2022). Esophageal squamous cell carcinoma (ESCC) is a type of esophageal carcinoma (EC) that can affect any part of the esophagus, but is usually located in the upper or middle third. "In addition, overexpression of SALL2 in radioresistant esophageal squamous cell carcinoma (ESCC) decreased cell migration and chemosensitivity." (PMID 36438565, 2022). "Contrary to the previous findings in ovarian and esophageal squamous cell carcinoma (ESCC) cancer cell lines, our studies showed that Sall2 promotes cell migration." (PMID 36438565, 2022).
lymphoma (2 papers, 2018 to 2021). A malignant (clonal) proliferation of B- lymphocytes or T- lymphocytes which involves the lymph nodes, bone marrow and/or extranodal sites.
Townes-Brocks syndrome (2 papers, 2014 to 2020). Townes-Brocks syndrome (TBS) is a rare genetic disorder characterized by the triad of imperforate anus, dysplastic ears often associated with sensorineural and/or conductive hearing impairment, and thumb malformations. "Functional redundancy between Sall factors is likely to compensate for the heterozygous loss of Sall2 in the eye, particularly Sall1 which is expressed in the developing eye and can be associated with retinochoroidal coloboma in some cases of Townes-Brocks syndrome." (PMID 24412933, 2014).
acute lymphocytic leukaemia (1 paper, 2024). "The METTL13 loci carried TOX high mobility group box family member 4 (TOX4) and spalt-like transcription factor 2 (SALL2) genes, and the expression of those genes was changed in the human acute lymphocytic leukaemia." (PMID 39596561, 2024).
adenoma (1 paper, 2025). A neoplasm arising from the epithelium. "In summary, SALL2 protein levels were significantly reduced in adenomas and adenocarcinoma tissues (p < 0.01) compared to in adjacent normal tissues." (PMID 40869218, 2025). "We found that SALL2 is expressed in normal colon tissues but is significantly downregulated in adenoma and carcinoma samples, as well as cancer cell lines." (PMID 40869218, 2025). "The percentage of SALL2-positive cells was 90.6% in adjacent normal tissues, 74.3% in adenomas, and 25.4% in CRC tissues." (PMID 40869218, 2025). "Immunohistochemical analysis revealed that SALL2 is present in the epithelium and stroma of normal colon tissue but is significantly downregulated in adenomas, carcinomas, and CRC cell lines." (PMID 40869218, 2025). "However, there was a significant decrease in nuclear SALL2 staining in both cell types as the tissue progressed from normal to adenoma and CRC." (PMID 40869218, 2025). "SALL2 may serve as a potential biomarker for the suspicion of polyps, as there was a significant downregulation of SALL2 in the early stages of CRC progression, such as adenoma, in our cohort." (PMID 40869218, 2025).
Blindness (1 paper, 2022). Blindness is the condition of lacking visual perception defined as a profound reduction in visual perception. "SALL2 deficiency leads to optic fissure closure failure, causing blindness." (PMID 36438565, 2022).
brain tumor (1 paper, 2021). "Loss of function experiments through the induction of the miR-302/367 cluster in U87 cells revealed the importance of SALL2 and the other three transcription factors in brain tumor malignancy." (PMID 34944911, 2021). "It was further supported by using lipopolymeric nanoparticle-containing combo siRNA (OLIG2, POU3F2, SALL2, and SOX2) targeting brain tumor-initiating cells (BTICs) in a mouse brain tumor model." (PMID 34944911, 2021).
Breast invasive carcinoma (1 paper, 2019). "Gene Set Enrichment Analysis (GSEA) of the Cancer Genome Atlas (TCGA) Breast invasive carcinoma (BRCA) dataset indicated that low expression of SALL2 correlates with a PI3K/Akt/mTOR signaling signature, suggesting that loss of SALL2 might activate PI3K/Akt/mTOR pathway." (PMID 31657150, 2019).
breast tumor (1 paper, 2019). "SALL2 expression was significantly lower in the tamoxifen‐treated ER+ breast tumors with relapse or metastasis than that in the primary tumors without relapse or metastasis." (PMID 31657150, 2019). "Importantly, doxycycline‐inducible mouse model revealed that restoration of SALL2 sensitized tamoxifen‐resistant breast tumor to tamoxifen therapy." (PMID 31657150, 2019).
cervical cancer (1 paper, 2021). A primary or metastatic malignant neoplasm involving the cervix. "The first study that associated SALL proteins with HPV-related cancer showed that oncoprotein E6 from HR-HPV infection binds SALL2 and induces its stabilization in cervical cancer cells." (PMID 34944911, 2021). "This interaction prevented the binding of SALL2 to the p21 promoter, leading to the accumulation of inactive SALL2 in SiHa, Caski, and HeLa HR-HPV positive cervical cancer cell lines." (PMID 34944911, 2021).
colon adenocarcinoma (1 paper, 2025). "Consistent with our findings, a recent large-scale bioinformatic study of cancer showed a positive correlation between SALL2 and the stromal score in colon adenocarcinoma (COAD), stomach adenocarcinoma (STAD), and rectal adenocarcinoma (READ)." (PMID 40869218, 2025). "However, in colon adenocarcinoma, SALL2 expression decreased in both cell types and increased in type 1 macrophages (CD68+)." (PMID 40869218, 2025).
gastric carcinoma (1 paper, 2017). A carcinoma that arises from epithelial cells of the stomach. "SALL2 is possibly an early tumour marker for gastric carcinomas and acts as a suppressor through hypermethylation of the SALL2 P2 promoter in OC." (PMID 29228922, 2017).
glaucoma (1 paper, 2021). Increased pressure in the eyeball due to obstruction of the outflow of aqueous humor. "Other variants in genes for IFT172, DFNB31, PDHX, SALL2, BMP4 and GPR179 by WES were excluded as deleterious and pathogenic mutations, and none of them was reported as a stronger/convincing glaucoma causing variant in the literature." (PMID 34399712, 2021).
hepatocellular carcinoma (1 paper, 2021). A malignant tumor that arises from hepatocytes. "The E1A isoform expression differs between many normal and cancer tissues, except in hepatocellular carcinoma (see SALL2-202)." (PMID 33692826, 2021).
lung adenocarcinoma (1 paper, 2023). A carcinoma that arises from the lung and is characterized by the presence of malignant glandular epithelial cells. "The results showed that, compared with normal samples, GMPR was under-expressed in tumors, MRPL13 was overexpressed in lung adenocarcinoma, while the expression of MCFD2 and SALL2 between normal lung tissue and lung adenocarcinoma tissue was not different." (PMID 37946181, 2023).
malignant glioma (1 paper, 2017). A grade III or grade IV glioma arising from the central nervous system. "SALL2 interacts with other transcription factors to participate in cell reprogramming and inhibition of the migration and invasion of malignant glioma cells following ionising radiation." (PMID 29228922, 2017).
metastatic tumors (1 paper, 2019). "Of importance, we found that SALL2 expression was significantly decreased in relapsed metastatic tumors compared to the paired primary tumors." (PMID 31657150, 2019).
neural tube defect (1 paper, 2024). A congenital defect characterized by failure of the neural tube to close completely; this results in the presence of openings in the brain or spinal cord. "Sall2 deficient mice may exhibit neural tube defect (NTD), depending on the genetic background, while compound deletion of Sall1, Sall2, and Sall4 led to more severe NTD, implying functional redundancy among Sal family members." (PMID 39349437, 2024).
rectal cancer (1 paper, 2025). A primary or metastatic malignant neoplasm that affects the rectum. "Further studies with additional patient cohorts, along with sequencing and transcriptome analyses, could help clarify the significance of SALL2 expression in colon and rectal cancers." (PMID 40869218, 2025).
Retinal coloboma (1 paper, 2014). A notch or cleft of the retina or choroid, located vertically below the optic disc. "Analysis of Sall2-deficient mouse embryos revealed delayed apposition of the optic fissure margins and the persistence of an anterior retinal coloboma phenotype after birth." (PMID 24412933, 2014).
retinochoroidal coloboma (1 paper, 2014). "Here, we report the identification of a novel homozygous mutation in the SALL2 gene using a combined strategy of homozygosity mapping and exome sequencing in three siblings from a consanguineous family with an iris and retinochoroidal coloboma phenotype." (PMID 24412933, 2014). "In summary, using a combined homozygosity mapping and exome sequencing approach, we have identified a novel homozygous mutation in SALL2 in three siblings variably affected with retinochoroidal coloboma." (PMID 24412933, 2014).
squamous cell carcinoma (1 paper, 2013). A carcinoma arising from squamous epithelial cells. "SALL2 was also identified among the overexpressed genes in squamous cell carcinoma (SCC) of the tongue, and was proposed as a prognosticator of head and neck SCC since its expression is associated with depth of invasion and advance T stage." (PMID 24040083, 2013).
testicular germ cell tumor (1 paper, 2013). A germ cell tumor arising from the testis. "Lately, a transcriptome study indicated that SALL2 is upregulated in Testicular Germ Cell tumor (TGC) and may be involved in TGC tumorigenesis." (PMID 24040083, 2013).